LINC01416 (long independently transcribed non-coding RNA 1416)
Gene: Long non-coding RNA gene on chromosome 18 (55,881,688 to 55,998,219, reverse strand). Ensembl gene ENSG00000260930.
Diseases named in the same sentence as LINC01416 in open-access papers:
LINC01416 is named in the same sentence as 1 disease in open-access papers, as found by Europe PMC text mining. Sharing a sentence is not in itself a finding about the gene and the disease.
LINC01416 shares sentences with these, for which no sentence is quoted: cancer (1 paper).